TRAF4 (TNF receptor associated factor 4)
Description:
Adapter protein with E3 ligase activity that is involved in many diverse biological processes including cell proliferation, migration, differentiation, DNA repair, platelet activation or apoptosis. Promotes EGFR-mediated signaling by facilitating the dimerization of EGFR and downstream AKT activation thereby promoting cell proliferation. Ubiquitinates SMURF2 through 'Lys-48'-linked ubiquitin chain leading to SMURF2 degradation through the proteasome and subsequently osteogenic differentiation. Promotes 'Lys-63'-mediated ubiquitination of CHK1 which in turn activates cell cycle arrest and activation of DNA repair. In addition, promotes an atypical 'Lys-29'-linked ubiquitination at the C-terminal end of IRS1 which is crucial for insulin-like growth factor (IGF) signal transduction. Regulates activation of NF-kappa-B in response to signaling through Toll-like receptors. Required for normal skeleton development, and for normal development of the respiratory tract (By similarity). Required for activation of RPS6KB1 in response to TNF signaling. Modulates TRAF6 functions. Inhibits adipogenic differentiation by activating pyruvate kinase PKM activity and subsequently the beta-catenin signaling pathway.
Synonyms: CART1; MLN62; RNF83
Tractability: Antibody: UniProt places it where antibodies can reach, with medium confidence; its Gene Ontology location is reachable by antibodies, with medium confidence. PROTAC: UniProt records ubiquitination sites on it; ubiquitination databases record sites on it; its protein half-life has been measured.
Gene: Protein-coding gene on chromosome 17 (28,744,011 to 28,750,956, forward strand). Ensembl gene ENSG00000076604.
Subcellular location: Cytoplasm; Nucleus; Cytoplasm, perinuclear region; Cell junction, tight junction; Cell membrane; Cytoplasm, cytoskeleton
Subcellular location (Human Protein Atlas): Nucleoli fibrillar center; Cytosol; Nucleoplasm
Gene Ontology:
Molecular function: identical protein binding; protein binding; thioesterase binding; tumor necrosis factor receptor binding; ubiquitin protein ligase activity; ubiquitin protein ligase binding; WW domain binding; signaling adaptor activity; enzyme binding; metal ion binding; protein kinase binding; zinc ion binding
Biological process: positive regulation of JNK cascade; positive regulation of protein kinase activity; cell surface receptor signaling pathway; regulation of canonical NF-kappaB signal transduction; proteasome-mediated ubiquitin-dependent protein catabolic process; regulation of apoptotic process; signal transduction
Cellular component: cytoplasm; cytosol; fibrillar center; nucleoplasm; nucleus; bicellular tight junction; cytoskeleton; perinuclear region of cytoplasm; plasma membrane
Genetic constraint (gnomAD): Loss-of-function variants: 9 observed, 45.79 expected, observed/expected ratio (o/e) 0.2, 90% interval 0.12 to 0.34. The upper end of that interval is the gene's LOEUF score, 0.34, which puts it in group 1 of 6, group 1 being the genes least tolerant of losing a copy. Missense variants: 448 observed, 629.04 expected, observed/expected ratio (o/e) 0.71, 90% interval 0.66 to 0.77. Synonymous variants: 236 observed, 243.25 expected, observed/expected ratio (o/e) 0.97, 90% interval 0.87 to 1.08.
Homologues: Orthologues: chimpanzee TRAF4 (100% identical), macaque TRAF4 (99% identical), rabbit TRAF4 (99% identical), guinea pig TRAF4 (98% identical), pig TRAF4 (98% identical), dog TRAF4 (97% identical), rat Traf4 (97% identical), mouse Traf4 (97% identical), tropical clawed frog traf4 (78% identical), zebrafish traf4a (77% identical), zebrafish traf4b (68% identical), Drosophila melanogaster Traf4 (42% identical). Paralogues in human: TRAF2 (31% identical), TRAF3 (30% identical), TRAF5 (30% identical), TRAF6 (25% identical), TRAF1 (20% identical).
Diseases named in the same sentence as TRAF4 in open-access papers:
TRAF4 is named in the same sentence as 79 diseases in open-access papers, as found by Europe PMC text mining. Sharing a sentence is not in itself a finding about the gene and the disease. The quoted sentences say what the papers report.
breast carcinoma (44 papers, 2008 to 2025). "Briefly, TRAF4 was found to be highly expressed in breast tumours and its expression is associated with disease- and relapse-free survival in breast cancer patients." (PMID 36944688, 2023). "To explore the association between TRAF4 and Eg5 in human breast cancer, we compared the protein level of Eg5 and TRAF4 in normal breast tissue (NBT) (n=16) and in breast cancer tissue (BCT) (n=78)." (PMID 35692762, 2022). "TRAF4 expression is suppressed in the nucleus of breast cancer cells and is associated with the invasive ability of breast cancer." (PMID 35242717, 2022). "In breast cancer, circMTO1 (hsa-circ-007874) interacts with TNF Receptor Associated Factor 4 (TRAF4), consequently inhibiting the mitotic kinesin Eg5 protein level and reversing monastrol resistance." (PMID 35205613, 2022). "Luminal A and B types are most common in male breast cancers, and increased TRAF4 gene copy number is present in male breast cancer patients with both, suggesting an association between TRAF4 and the molecular staging of male breast cancer." (PMID 35242717, 2022). "TRAF4 nucleus staining was more pronounced in breast tumour specimens than normal breast tissue, and high TRAF4 nucleus expression was significantly associated with poorer overall survival in breast cancer patients." (PMID 35242717, 2022). "In breast cancer patients, elevated TRAF4 expression is associated with increased phosphorylated SMAD2 and phosphorylated TAK1 and poor prognosis." (PMID 35242717, 2022). "In mammary cancer cells, TNF receptor-associated factor 4 (TRAF4) is amplified and promotes cancer cell invasion and metastasis." (PMID 35625561, 2022). "An observed overexpression of TRAF4 suggested that it is associated with the initiation and progression of primary breast cancer and metastasis." (PMID 32188842, 2020). "This study indicated that the nuclear localization of TRAF4 was associated with a poor survival rate in breast cancer patients following adjuvant chemotherapy." (PMID 25738361, 2015). "In this study, we show for the first time that the cytoplasm expression of TRAF4 in human breast-carcinoma was significantly associated with p70s6k activation and poor patient survival." (PMID 25738361, 2015). "Tumor necrosis factor (TNF) receptor-associated factor 4 (TRAF4) was initially identified as a gene amplified and overexpressed in breast carcinoma." (PMID 24396457, 2014). "Tumor necrosis factor receptor-associated factor 4 (TRAF4) was originally identified as a gene overexpressed in breast carcinoma." (PMID 24311986, 2013). "This study indicated that TRAF4 nuclear localization in breast tumors was associated with poor survival in breast cancer patients after adjuvant therapy." (PMID 24311986, 2013). "The Tumor Necrosis Factor (TNF) Receptor Associated Factor 4 (TRAF4) gene was identified due to its high expression in breast cancers." (PMID 24212830, 2011). "Further validation supported our hypothesis, as evidenced by the positive association between TRAF4 and IL‐8 protein expression in breast cancer tissues." (PMID 39716976, 2025). "TRAF4 up-regulates Eg5 protein levels by inhibiting Eg5 ubiquitination, thus preventing Eg5 degradation (and associated mitotic defects), and in doing so TRAF4 promotes breast cancer cell proliferation and inhibits breast cancer cell apoptosis." (PMID 35692762, 2022). "TRAF4 overexpression in breast cancer patients was significantly associated with poor prognosis." (PMID 35242717, 2022). "Moreover, we found that cytoplasmic TRAF4 expression in breast cancer patients was significantly associated with a poor prognosis." (PMID 25738361, 2015). "Notwithstanding, evidence from meta-analysis and bioinformatics validations indicates that TRAF2 and TRAF4 are highly expressed in primary and metastatic tumours, and their elevated level of expression is associated with metastasis and survival rate in breast cancer patients." (PMID 36944688, 2023).
breast carcinoma (continued). "Moreover, TRAF4 expression was associated with invasion, migration and metastasis in breast cancer." (PMID 29343747, 2018). "Importantly TRAF4 overexpression has been associated with a poor prognosis in breast cancers." (PMID 24311986, 2013). "Our analysis of the TCGA database showed a strong positive correlation between TRAF4 and IL‐8 gene expression in breast cancer and glioma." (PMID 39716976, 2025). "TRAF4 can lead to trastuzumab resistance in HER2-positive breast cancer by regulating the ErbB2 signaling pathway." (PMID 39075515, 2024). "TRAF4 modulates canonical signaling in breast cancer cells by ubiquitinating SMURF2 for destruction and mediates non-canonical signaling in a Traf6-independent manner, stabilizing TGFBR at the plasma membrane." (PMID 38313020, 2024). "TRAF4 was initially identified as an amplified gene in human breast carcinoma, and overexpression of TRAF4 protein occurs in other human cancers." (PMID 39710325, 2024). "Breast cancer cells with high levels of TRAF4 are more resistant to nitric oxide-induced cell death, similar to cells with high levels of SRC-3." (PMID 36625999, 2023). "Our research identified 7 human studies that examined the association of TRAF2 (1 study), TRAF4 (3 studies), and TRAF6 (3 studies) with survival rate in breast cancer patients (719 patients)." (PMID 36944688, 2023). "High TRAF4 expression has been detected in different cancers, such as hepatocellular carcinoma, endometrial cancer, and breast cancer." (PMID 36625999, 2023). "Previous studies have shown that breast cancer patients with high TRAF4 expression have poor prognosis." (PMID 36625999, 2023). "TRAF4 modulates cell proliferation, apoptosis, migration, and invasion in breast cancer and other cancer types." (PMID 36625999, 2023). "In particular, in breast cancer, TRAF4 is a key determinant of breast cancer pathogenesis by regulating the TGF-β pathway." (PMID 37568704, 2023). "Previous studies have suggested that TRAF4 is critical for breast cancer development and acts downstream of SRC-3." (PMID 36625999, 2023). "In breast cancer, TRAF4 inhibits apoptosis and promotes tumor cell proliferation by suppressing the ubiquitination of the spindle assembly-associated protein Eg5." (PMID 36765039, 2023). "Overexpression of TRAF4 led to trastuzumab resistance by activating HER2 signaling in HER2-positive breast cancer." (PMID 36765039, 2023). "In summary, our study suggests a new direction for investigating the role of TRAF4 in driving breast cancer progression." (PMID 35692762, 2022). "Based on data extracted from the TCGA data set, we initially discovered a significant increase of TRAF4 mRNA level in breast cancer patient samples versus normal breast samples." (PMID 35864174, 2022). "TRAF4 is a protein dynamically localized to the TJ and overexpressed in cancer and plays multiple functions in breast cancer progression." (PMID 35242717, 2022). "Through the NF-κB signaling pathway, TRAF4 promotes cancer cell proliferation in breast cancer, oesophageal cancer, osteosarcoma, and chronic lymphocytic leukemia." (PMID 35242717, 2022). "Relying on its Zinc fingers domain, TRAF4 interacted with Eg5 in the cytoplasm of breast cancer cells." (PMID 35692762, 2022). "We observed that TRAF4 upregulation is one strategy employed by HER2 + breast cancer cells to stabilize HER2 and desensitize Trastuzumab." (PMID 35864174, 2022). "Then, we performed an immunofluorescence assay to identify the subcellular localizations of TRAF4/SMURF2/HER2 in HER2+ breast cancer cells." (PMID 35864174, 2022). "TNF receptor-associated factor 4 (TRAF4), a unique TRAF family member, was initially identified from human metastatic lymph nodes of breast cancer." (PMID 36535926, 2022). "TRAF4 nucleus expression was significantly higher in non-invasive ductal carcinoma than in invasive ductal carcinoma, and TRAF4 nuclear expression was negatively correlated with breast cancer invasiveness." (PMID 35242717, 2022).
breast carcinoma (continued). "TRAF4/SMURF2/HER2 complex formation was verified by co-immunoprecipitation analysis in four HER2-positive breast cancer cell lines studied and in transiently transfected HCC1954 cells and HEK293T cells." (PMID 35864174, 2022). "TRAF4 upregulates PRMT5 expression in the nucleus, and PRMT5 forms a specific zinc finger structure with TRAF4, which plays an essential role in activating the NF-κB signaling pathway and promotes breast cancer cell proliferation." (PMID 35242717, 2022). "Girdin is mainly expressed in the cytoplasm of breast cancer cells, and TRAF4 facilitates its translocation to the nucleus." (PMID 35242717, 2022). "Breast cancer cell proliferation is dependent mainly on TRAF4, and overexpression of TRAF4 can contribute to breast cancer progression by destabilizing the tight junctions (TJs) between cells, thereby promoting cell migration." (PMID 35242717, 2022). "Consistent with the previous results, the protein level of Eg5 and TRAF4 were high in breast cancer tissues (in comparison with matched normal tissues), and a positive correlation between them was observed (p<0.05)." (PMID 35692762, 2022). "Through cell viability assay, colony formation assays and nude mice tumorigenesis experiment, we demonstrate TRAF4 promotes the proliferation of breast cancer cells by up-regulating Eg5 protein levels." (PMID 35692762, 2022). "In the present study, we found that Eg5, which has the function of inhibiting apoptosis, and TRAF4 are both highly expressed in breast cancer, and that the protein level of TRAF4 and Eg5 are positively correlated." (PMID 35692762, 2022). "By studying tissue samples from 80 breast cancer patients (invasive ductal carcinoma, clinical-stage II-III) diagnosed by puncture biopsy, breast cancer patients with low TRAF4 expression benefited most from chemotherapy." (PMID 35242717, 2022). "In breast cancer, TRAF4 promotes cancer cell migration and invasion through the Rac1 signaling pathway." (PMID 35242717, 2022). "Using the TCGA breast cancer cohorts, we found that HER2 and TRAF4 were amplified in 14% and 5% of all breast cancer respectively, and their amplifications were co-occurring in some cases." (PMID 35864174, 2022). "Taken together, these results implicated a potential role of the signaling adapter protein TRAF4 in the HER2-amplified subtype of breast cancer." (PMID 35864174, 2022). "Our study uncovers a new aspect of TRAF4 function in spindle assembly through regulation of Eg5 protein levels during mitosis, providing a new research direction for elucidating the role of TRAF4 in driving breast cancer progression." (PMID 35692762, 2022). "In epithelial breast cancer cells, TRAF4 depletion impairs EMT, while in mesenchymal-like cells, TRAF4 deficiency leads to loss of cell mobility." (PMID 35242717, 2022). "TRAF4 and Eg5 were both highly expressed in breast cancer and their protein level was positively correlated." (PMID 35692762, 2022). "TRAF4, a protein originally discovered in breast cancer-derived metastatic lymph nodes, has been shown to play an important role in breast cancer progression." (PMID 35692762, 2022). "To confirm these results, we detected the protein level of Eg5 and TRAF4 in matched normal and breast cancer fresh tissues from 16 patients." (PMID 35692762, 2022). "The level of MMP2 protein decreased and the level of E-cadherin protein increased, which verified that the metastasis ability of glioblastoma cells was inhibited, which is consistent with the regulatory mechanism involved in TRAF4 in breast cancer." (PMID 36077559, 2022). "CircMTO1 represses cell viability of and attenuates monastrol resistance by modulating the TRAF4/Eg5 signaling in breast cancer." (PMID 33686957, 2021). "To further confirm that the TRAF4-IRS-1 interaction exists in breast cancer cells, we immunoprecipitated endogenous TRAF4 from MCF-7 cells and demonstrated a strong interaction with IRS-1." (PMID 33991522, 2021).
breast carcinoma (continued). "In contrast, monastrol resistance can be reversed in breast cancer via the TRAF4/Eg5 pathway through overexpression of circMTO1." (PMID 32758239, 2020). "TRAF4 catalyzes K48-linked ubiquitination of SMURF2 to downregulate SMURF2 and promote breast cancer metastasis." (PMID 32357935, 2020). "Previous studies have demonstrated that abnormal expression of TRAF4 plays an important role in the pathogenesis of allergic airway inflammation, breast cancer, lung cancer and prostate cancer." (PMID 31076633, 2019). "For example, TRAF4 was shown to antagonize Smurf2 to promote metastatic breast cancer cell migration." (PMID 31076633, 2019). "TRAF4 was firstly identified in breast carcinomas and represents the first member of the TRAF family to be increased and expressed in human cancers." (PMID 30186853, 2018). "In a previous study, TGF-β activated the E3-ligase of TRAF4 through K63-linkage poly-ubiquitination, resulting in TRAF4-mediated stabilization of TβRI and promotion of TβRI signaling in breast cancer cells." (PMID 28827764, 2017). "By studying the relationship between TRAF4 and 70 kDa ribosomal protein S6 kinase (p70s6k) in vivo, we demonstrated that cytoplasmic TRAF4 was correlated with the activation of p70s6k in breast cancer." (PMID 25738361, 2015). "According to relative expression level of TRAF4 to Actin, we divided the breast cancer samples equally into two groups, TRAF4 low expressers and high expressers." (PMID 25738361, 2015). "In summary, we demonstrated that cytoplasmic TRAF4 has pivotal roles in regulating the activation of p70s6k signaling in breast cancer." (PMID 25738361, 2015). "We analyzed the relationship between TRAF4 with the overall survival of these breast cancer patients after surgery was performed by the Kaplan-Meier method." (PMID 25738361, 2015). "Recently, one report revealed the significance of the nuclear localization of TRAF4 in breast cancers." (PMID 25738361, 2015). "Basing on the interaction of TRAF4 and p70s6k, we further analyzed their relationship with immunohistochemistry and western blot in breast cancer tissues (in vivo)." (PMID 25738361, 2015). "In summary, our work suggests a new direction for understanding the oncogenic function of TRAF4 in breast cancer." (PMID 25738361, 2015). "Dramatically elevated TRAF4 was observed in breast cancer tissues than in paired normal breast tissue (p < 0.05, Student's t test)." (PMID 25738361, 2015). "Here, we demonstrated that TRAF4 promotes the proliferation of breast cancer cell MCF7 predominantly through the p70s6k/S6 pathway, with the Zinc fingers domain playing a key role." (PMID 25738361, 2015). "These seemingly disparate results show that both cytoplasmic and nuclear TRAF4 expressions played an important role in progression of breast cancer through different pathways." (PMID 25738361, 2015). "This is consistent with the expression of TRAF4 in breast cancer tissues reported in our previous study." (PMID 24396457, 2014). "The present study investigated the expression and location of TRAF4 in breast cancer cells and the biological function of TRAF4 in MCF-7 cells." (PMID 24396457, 2014). "Firstly, the cellular localization of TRAF4 was confirmed in the breast cancer MCF-7 cells through immunofluorescence staining." (PMID 24396457, 2014). "Originally identified as a protein localized in the nuclei of breast carcinoma cells, TRAF4 has also been previously detected in the cytoplasm." (PMID 24396457, 2014). "The present study investigated the expression and anti-apoptotic function of TRAF4 in human breast cancer MCF-7 cells." (PMID 24396457, 2014). "The results of the present study showed that, in vitro, TRAF4 exhibits higher expression in breast cancer cells than in normal breast cells." (PMID 24396457, 2014). "A recent report shed light into the significance of the nuclear localization of TRAF4 in breast cancers." (PMID 24311986, 2013).